BRAF (B-Raf proto-oncogene, serine/threonine kinase)
Diseases named in the same sentence as BRAF in open-access papers (continued):
Sharing a sentence is not in itself a finding about the gene and the disease.
cancer (continued). "The efficacy of BRAF or MAPK inhibitors in such cancer patients requires further investigation in prospective studies." (PMID 39018217, 2024). "In a Cancer Genome Atlas study that analyzed the molecular profile of almost 500 cases of PTC, BRAF mutations accounted for 61.7% of all mutations; most mutations were substitutions at codon V600." (PMID 39336882, 2024). "NRG1 is expressed in multiple types of cancer cells and is implicated in therapy resistance to EGFR-targeting antibody cetuximab in CRC, RAF inhibitors in BRAF mutant melanoma, and MEK inhibitors in metastatic uveal melanoma." (PMID 39199625, 2024). "MOSA accurately reconstructed gene dependencies, for example, BRAF dependency in BRAF gain-of-function mutant cancer cell lines, and FLI1 dependency in cell lines harboring an FLI1-EWSR1 fusion gene." (PMID 39614072, 2024). "It appears that the activation of BRAF by the PCAIs helps trigger the shrinking of cancer cells, as was elucidated in previous studies, since increased activation of BRAF is associated with senescence, a possible potent anticancer mechanism." (PMID 39436906, 2024). "Our analysis of a large cohort of BRAF mutant cancers will help identify subsets of populations that would benefit from novel targeted therapies." (PMID 38275886, 2024). "From a vertical signaling cascade standpoint, the three commonly mutated effectors of the ERKp in human cancer are arranged as EGFR, KRAS, and BRAF." (PMID 38485987, 2024). "Altogether, this represents another mechanism of BRAF activation in cancer, whereby BRAF kinase expression is driven by aberrant transcriptional activity." (PMID 39018217, 2024). "Nevertheless, the 85–88% response rate with this well-tolerated regimen is noteworthy and demonstrates the potential of autophagy inhibition for BRAF mutant cancers." (PMID 39272847, 2024). "The combination of vemurafenib and everolimus (anti-mTOR) demonstrated promising activity in 20 patients with BRAF-mutant advanced cancers (1 NSCLC), including those previously treated with a BRAF inhibitor." (PMID 39684685, 2024). "Preclinical studies of KRAS- and BRAF-mutated CRC noticed the necessity of dual inhibition of MEK and PIK3CA pathways in the animal model of cancer." (PMID 39056802, 2024). "Due to these pro-growth and pro-survival functions, cancer cells can develop “oncogenic addiction” towards BRAF’s signaling activity." (PMID 39018217, 2024). "We found that composite mutations occur in 5% of cancer patients, mostly affecting the PIK3CA, EGFR, BRAF, and KRAS genes, which are common precision medicine targets." (PMID 38757376, 2024). "Given the increasing use of BRAF inhibitors as well as checkpoint blockade inhibitors to treat a number of cancers, we will discuss the clinical implications of the presence of BRAF V600E mutation and PD-L1 expression in RDD." (PMID 39592527, 2024). "In our experiments, the only genes in which THCA is included as a held-out cancer type are BRAF and NRAS; generalization performance for both genes is below cross-validation performance but slightly worse for NRAS than BRAF." (PMID 39776849, 2024). "Although similar mutations in other cancers, such as ALK, EGFR, and KRAS in lung cancer or BRAF in melanoma, have revolutionized cancer treatment, identifying analogous markers in GBC is challenging due to its genetic heterogeneity." (PMID 39683528, 2024). "Unexpected off-target activities have thus made it difficult for small-molecule BRAF inhibitors to develop into a new cancer medicine." (PMID 38791574, 2024). "This classification sheds light on the functionality and interactions of mutant BRAF proteins within cellular signaling networks, thereby providing critical insights into their contributions to cancer development and progression." (PMID 39156294, 2024). "The use of antibodies in the treatment of BRAF-mutant cancers is reflective of a growing interest in immunotherapy, both within the field of oncology and beyond it." (PMID 38539548, 2024).
cancer (continued). "While most cancer patients show favorable initial responses to BRAF inhibitors, resistance occurs once the ERK pathway is reactivated." (PMID 39000097, 2024). "Although BRAF inhibitors have shown efficacy in various cancers, most patients eventually develop resistance." (PMID 38655260, 2024). "Consistent with previous reports, canonical cancer gene mutations in EGFR, ERBB2, and BRAF were always truncal as early as the AAH/AIS stage, suggesting that these mutations are very early genomic events before the acquisition of invasiveness." (PMID 38764572, 2024). "Ten tumors were negative for mutations in KIT, PDGFRA, and RAS-pathway genes (BRAF, RAS isoforms, and NF1), and for all other 161 cancer-relevant genes that were included in our NGS panel." (PMID 39199677, 2024). "Extending the follow-up periods, exploring combined markers such as BRAF V600E, and investigating the mechanisms of Ki-67 in various cancer subtypes can offer greater insights and improve prognostic accuracy." (PMID 39057172, 2024). "BRAF, as a serine/threonine kinase, is overactivated by a point mutation, inducing the RAS-RAF-MEK-ERK-MAP kinase pathway and leading to cancer’s proliferation." (PMID 39272320, 2024). "Out of the set of molecular genetic events in patients with PTC, the ATA guidelines (2015) recommend using only the BRAF and TERT mutations as markers of cancer with the least favorable prognosis." (PMID 39000197, 2024). "Alterations of the BRAF gene and the resulting changes in the BRAF protein are one example of molecular cancer profiling in humans and dogs." (PMID 39591358, 2024). "BRAF and MEK inhibitors (BRAFi and MEKi) represent a breakthrough in the treatment of BRAF(V600E)-mutant cancers, greatly improving outcomes for cancer patients." (PMID 39052013, 2024). "Targeted approaches in cancer management have been met with great success in various cancer types including BRAF in breast cancer or EGFR and KRAS in lung cancer." (PMID 39360054, 2024). "We found trametinib, a selective MEK inhibitor FDA-approved for BRAF mutant cancers, greatly enhanced the localization of desmosomal proteins to cell-cell junctions in NHEKs despite treatment with dabrafenib or vemurafenib." (PMID 39325541, 2024). "Uncontrolled cell proliferation and the advancement of cancer are outcomes of BRAF mutation; approximately 90% of CRC cases originate from the serrated pathway, conferring an increased risk of cancer-specific mortality." (PMID 39467702, 2024). "We conducted experiments to assess HAMLET’s impact on mitochondrial respiration in HT-29 and WiDr cancer cells, displaying similar BRAF mutant genetic characteristics." (PMID 38256402, 2024). "Although all RAF kinases promote MAPK signaling, BRAF is the most consistently altered RAF family gene across human cancers." (PMID 39018217, 2024). "Recently, a new focus has been on developing paradox breakers and type II pan-RAF inhibitors that ablate the upregulated MAPK activity seen in Class II and III BRAF-altered cancers treated with currently FDA-approved RAF inhibitors." (PMID 39018217, 2024). "Given their frequency along with advancements in screening technologies, various methods are used for the detection of BRAF-mutant cancers." (PMID 38539548, 2024). "There has also been some headway on incorporating theranostic treatment options, such as photodynamic therapy (PDT), into the arsenal of approaches that can be used to treat BRAF-mutant cancers." (PMID 38539548, 2024). "Our findings suggest that MAP3K3 is a promising target for alleviating drug resistance and that combination treatment with ponatinib with inhibitors of BRAF or CDK4/6 should be further tested as a YAP-targeting strategy in cancer treatment." (PMID 38622197, 2024).
cancer (continued). "In conclusion, our study reveals a previously unrecognized mechanism for the regulation of YAP stability, suggesting MAP3K3 inhibition as a promising strategy for overcoming resistance to CDK4/6 and BRAF inhibitors in cancer treatment." (PMID 38622197, 2024). "Two promising examples of this are plixorafenib and PLX904; they not only inhibit monomeric BRAF V600E-mutant cancers but can also inhibit BRAF homodimers and BRAF-CRAF heterodimers." (PMID 38539548, 2024). "We found that the signature was upregulated during malignant transformation and cancer progression, and it was particularly enriched in CRCs with mutant BRAF compared to wild-type counterparts." (PMID 38731846, 2024). "Next, we continued our selectivity assessmentby testing the antiproliferative activity of the top three compoundsfrom each round on KRAS, HRAS, or BRAF mutant cancer cells." (PMID 38758695, 2024). "Current FDA-approved BRAF/MEK inhibitors are being further explored in different treatment combinations across various cancers." (PMID 38203795, 2024). "Here we discuss the diverse forms of BRAF alterations found in human cancers and the strategies to inhibit them in patients harboring cancers of distinct origins." (PMID 39018217, 2024). "Studies have shown that using BRAF inhibitors can paradoxically lead to the activation of the MAPK pathway, and this is associated with the progression of the cancer." (PMID 39518080, 2024). "BRAF and MEK inhibitors are commonly used in combination treatments for other cancers with high rates of RAS and CDKN2A mutations." (PMID 38612819, 2024). "Targeted therapies have significantly improved clinical outcomes in patients with various cancer such as BRAF and MEK/ERK inhibitors in metastatic melanoma." (PMID 38461299, 2024). "With advancements in detection technologies, several approaches to the treatment of BRAF-mutant cancers have been taken." (PMID 38539548, 2024). "A recent analysis of the TCGA dataset showed high BRAF mRNA expression in several cancer types including cervical, colon, esophageal, hepatocellular, lung, gastric, and uterine cancers as well as cholangiocarcinoma." (PMID 38919805, 2024). "The RAS-regulated RAF–MEK1/2–ERK1/2 signalling pathway is activated in cancer due to mutations in RAS proteins (especially KRAS), BRAF, CRAF, MEK1 and MEK2." (PMID 38381045, 2024). "With the advancements in diagnostic technologies, a wide range of methods exist for the detection and diagnosis of BRAF-mutant cancers." (PMID 38539548, 2024). "BRAF-induced MAPK activation cannot be controlled with MEK inhibition only and requires combined MEK and BRAF inhibition, whereas the activation can be controlled reasonably well in RAS mutation-initiated cancers." (PMID 38672667, 2024). "The first subgroup is a CIMP-high subgroup exhibiting a very high frequency of cancer-specific DNA hypermethylation, which is associated with MLH1 methylation and the BRAF V100E mutation." (PMID 38314203, 2024).
cancer (continued). "We analyzed 8,805 3’ kinase gene fusions curated from the COSMIC, focusing on the seven most common kinase fusions involving ALK, RET, ROS1, NTRK1, NTRK3, ABL1, and BRAF genes found in various types of cancers." (PMID 38877018, 2024). "In turn, CAF activation elicits BRAF downstream signaling in resistant cancer cells and promotes cell survival." (PMID 38448544, 2024). "Meanwhile, MTOR was found to be linked to PIK3C; BRAF and MAPK1 were found to be linked to EGFR; and ERBB2 and ALK are linked to the common NSCLC and Cancer pathway." (PMID 38921583, 2024). "Twenty-five (24.8%) indeterminate nodules presented mutations in cytology samples, with one RAS mutation in a benign lesion and twenty-four in malignant tumors, being thirteen (17.3%) for RAS mutation, seven (9.3%) for BRAF, and four (5.6%) for TERTp mutation." (PMID 38337794, 2024). "In contrast, mutations in three other genes of the KRAS pathway, BRAF, SOS1, and NF1, were significantly more common in CDX2-suppressed cancers." (PMID 39452477, 2024). "The inhibition of BRAF has excellent potential in developing and identifying useful substances for cancer treatment." (PMID 38999138, 2024). "Our studies on tissues from patients with benign and malignant thyroid lesions showed a significant contribution of the BRAF V600E mutation and changes in the expression of RASSF1A, DIRAS3, and AKAP9 genes in developing this type of cancer." (PMID 38203733, 2024). "The discovery of BRAF mutations, particularly BRAFV600E mutation, as drivers in various cancers provided a rationale for pharmacological targeting of the BRAF oncoprotein." (PMID 38731852, 2024). "Our study is the first to observe the activation of several diverse pathways in cancer cells adapting to targeted EGFR or BRAF inhibition." (PMID 38473364, 2024). "Although all three RAF kinases play essential roles in normal mammalian cells, it is predominantly BRAF that is altered in cancer." (PMID 38787171, 2024). "Accordingly, the inhibition of V600E mutant BRAF is considered a promising strategy for the development of new cancer medicines." (PMID 38791574, 2024). "The BRAF gene also possesses an excellent ability to distinguish between benign and malignant tumors." (PMID 39205691, 2024). "HSPA9 not only modulates the Raf/MEK/ERK signaling pathway but also promotes the PP1α-MER1/2 interaction to increase MEK1/2 dephosphorylation in KRAS and BRAF mutant cancer cells." (PMID 39261452, 2024). "What’s more, heat shock protein 90 (HSP90) cooperates with its co-chaperone cell division cycle 37 (CDC37, highly expressed in endothelial cells) to support multiple protein kinases involved in cancer progression, including BRAF." (PMID 38233802, 2024). "The mutation frequencies in BRAF, TERT, RET, ATM and GGT1 were significantly higher in cancer tissues than benign nodules." (PMID 38886866, 2024). "The patient's cancer responded to rechallenge with BRAF- and EGFR-targeted therapy with a rapid decline in CA19-9 levels, BRAF-V600E allele frequencies (0.3%-0.4%), as well as a radiographic response of the new lesions." (PMID 39626159, 2024). "Since 2013, the Cancer Hospital of the Chinese Academy of Medical Sciences has adopted VENTANA anti-BRAF V600E (VE1) Mouse Monoclonal Primary Antibody as one of the standard reagents for the IHC method of detecting BRAF V600E mutations." (PMID 39464719, 2024). "One study found that isolated BRAF inhibition in cancer cells leads to the overexpression of the receptor tyrosine kinase c-Met." (PMID 39036614, 2024). "To provide an external validation for our findings, we interrogated the Cancer Cell Line Encyclopedia via cBioPortal13-16 for NSCLC cell lines harboring BRAF class 3 mutations." (PMID 39637338, 2024).
cancer (continued). "BRAF, integral to the MAPK/ERK signaling pathway, plays a significant role in cancer progression, and its mutations are associated with enhanced cell growth and survival." (PMID 38794205, 2024). "In order to continue to advance in this field, it is imperative that this system be maintained to better the lives of patients with BRAF-mutant cancers." (PMID 38539548, 2024). "BRAF genomic alterations are common in many cancer types and have proven to be potent oncogenic drivers." (PMID 38275886, 2024). "We would also like to mention that our patient had a BRAF V600E mutation, which was considered only until recently to be more a marker for the sporadic MSI cancer." (PMID 38957326, 2024). "ACA-28 and its lead compound ACAGT-007a were shown to induce apoptosis in cancer cell lines with different oncogenic mutations, ranging from HER2, BRAF, NRAS, and KRAS." (PMID 38500550, 2024). "Mutations affecting components of the MAPK pathway are common in various cancer types, making the inhibition of BRAF and MEK, and consequently the suppression of downstream signaling, a promising therapeutic strategy." (PMID 39582535, 2024). "Proteomic analysis identifies adenine nucleotide translocase 3 (ANT3) as an interacting protein of HSPA9 and indicates that HSPA9 can disrupt the interaction between ANT3 and cyclophilin D (CypD) in BRAF mutant cancer cells." (PMID 39261452, 2024). "To elucidate the resistance mechanism, we conducted a comprehensive analysis using the FoundationOne CDx cancer gene panel test, revealing the presence of a KRAS Q61H mutation alongside the BRAF V600E mutation." (PMID 38962037, 2024). "Multiple variables were assessed, including age, sex, cancer type, baseline laboratory markers (neutrophil or lymphocyte count; LDH), and BRAF mutation status." (PMID 38248113, 2024). "In these cancer types, tumors with Class I alterations can be treated with BRAF inhibitors or combinations of BRAF/MEK inhibitors." (PMID 39018217, 2024). "For an additional 2 carcinomas with RAS variants, 1 in ATC was found coexisting with both BRAF V600E and TERT promoter variants, and the other in MTC coexisting with BRAF V600E alone." (PMID 38758552, 2024). "Patients with high-grade carcinoma had significantly higher expression of the BRAF gene compared to their counterparts with low-to-moderate grade tumors (p < 0.001)." (PMID 38919805, 2024). "BRAF is pivotal in cancer treatment, especially for melanoma and colorectal cancer, driven by frequent V600E mutations promoting tumor growth." (PMID 37764362, 2023). "These responses provide a mechanistic explanation for the efficacy of BRAF-targeted therapy for some cancers and the intrinsic resistance in others." (PMID 38136350, 2023). "On the basis of US results, presence of the BRAF gene, and cytopathology, patient cancers were defined as malignant, benign, or undetermined." (PMID 36765671, 2023). "In the AUS-other subcategory, not only were PTCs rarer among cancers, but BRAF was also less likely to be positive (only 1/4 PTCs were BRAF-positive among AUS-other nodules vs. 3/4 among AUS-nuclear nodules)." (PMID 37686562, 2023). "Clinically, the development of resistance to BRAF inhibitors often involves the selection of pre-existing subpopulations of cancer cells with alternative genetic alterations." (PMID 38067230, 2023). "Alteration of common oncogenic proteins, such as epidermal growth factor receptor (EGFR), KRAS, BRAF, and c-Myc, drives tumorigenesis across 38 cancer types." (PMID 36694209, 2023).